CRP (C-reactive protein)
Diseases named in the same sentence as CRP in open-access papers (continued):
Sharing a sentence is not in itself a finding about the gene and the disease.
dementia (continued). "PD patients with dementia also showed significantly higher levels of C-reactive protein (CRP) compared to non-demented PD patients (p=0.032) and to the reference group (p=0.026)." (PMID 25411230, 2014). "Most studies measure CRP at a single time-point, which may not accurately capture the inflammatory processes relevant to dementia development." (PMID 39913250, 2025). "The results show that there may not be a linear relationship between hs-CRP and dementia and between hs-CRP and AD, but there is a relationship between elevated hs-CRP and dementia, especially AD." (PMID 38548879, 2024). "Contrary to hypothesis 2, CRP did not mediate the association between the ILB and dementia incidence (indirect effect a*b: B = −0.011, Bc 95% CI: −0.028 0.004)." (PMID 38706574, 2024). "The total effect of the ILB on dementia was positive and significant (total effect c: B = 0.186, 95% CI: 1.064, 1.362, p = 0.003) and did not change significantly after controlling for CRP at wave 6 (direct effect c': B = 0.196, 95% CI: 0.072, 0.320, p = 0.002)." (PMID 38706574, 2024). "However, the proportion of incident dementia cases across quartiles of the CRP distribution did not substantially differ." (PMID 37066239, 2023). "The reason may lie in the complex non-linear relationships between CRP levels and incident dementia, which cannot be captured adequately by a linear model." (PMID 38071240, 2023). "Moreover, CSF CRP levels are higher in patients with PD-related dementia as compared to PD patients without dementia and are also associated with severity of depression, anxiety, and fatigue in PD." (PMID 37251392, 2023). "Meanwhile, we investigate the associations between IgG N-glycan profiles and inflammation factors including anti-inflammatory (IL-4 and IL-10) and proinflammatory factors [IL-1β, IL-6, CRP, TNF-α, and interferon-gamma (IFN-γ)], which may further explain the role of IgG glycosylation in dementia." (PMID 33542243, 2021). "Furthermore, we analyzed the association between IgG N-glycome and markers of inflammation including anti-inflammatory (IL-4 and IL-10) as well as proinflammatory factors (CRP, TNF-α, IFN-γ, IL-1β, and IL-6), contributing to explain the role of IgG glycosylation on dementia." (PMID 33542243, 2021). "In contrast, C reactive protein was not altered between dementia and non-dementia subjects." (PMID 26806700, 2016). "The regression coefficients of baseline CRP for the two periods were 1.41 (95% confidence interval [CI] 0.21–2.61) and 2.62 (95% CI 0.25–4.98), respectively, after adjusting for sex, age, baseline UPDRS-III score, dementia, and incremental L-dopa equivalent dose." (PMID 26308525, 2015). "However, because this was a cross-sectional study, it is not possible to determine if elevated CRP levels occur before the development of dementia or are a consequence of the disease." (PMID 24587705, 2014). "Furthermore, additional adjustment for age, sex, PEG, cerebrovascular diseases, severe dementia, neuromuscular diseases, aspiration pneumonia, chronic heart failure, total lymphocyte count (mm3), and c-reactive protein (mg/dl) did not substantially change the results." (PMID 35840689, 2022). "Comparison of serum levels of pro-inflammatory cytokines, CRP and TGF-β at baseline and follow-up visits were not significantly different between participants with dementia, MCI, or without cognitive impairment." (PMID 41384827, 2025). "Unexpectedly, inflammatory markers, CRP, IL-1β, IL-6, and TNF-α did not discriminate dementia cases from non-cases." (PMID 37605096, 2024). "In the present study, we did show a positive correlation of resistin with inflammatory indicators (interleukin-6 and CRP) and a negative correlation with anti-inflammatory markers (HDL-C and PON1 activity) in all dementia patients." (PMID 28421328, 2017).
dementia (continued). "Furthermore, CRP levels were significantly higher in the CSF of patients with PD with dementia (PDD) compared with patients with PD without dementia and HCs, but it was not possible to distinguish between patients with PD without dementia and HCs." (PMID 37815899, 2024). "In another study, an elevated level of C-reactive protein (CRP), a non-specific marker for inflammation, was found in the cerebrospinal fluid (CSF) and serum from patients with mild cognitive impairment (MCI), which is considered as an early stage of AD and other dementia." (PMID 35693341, 2022).
hyperlipidemia (256 papers, 2007 to 2026). "LASSO-logistic regression analysis identified seven predictors associated with PSS: C-reactive protein, albumin, creatine kinase, fasting blood glucose, hyperlipidemia, sleep disorders, and manual muscle testing (MMT) score at admission." (PMID 41432712, 2026). "Through rigorous analysis, BMI (Body Mass Index), fasting blood glucose, serum uric acid, C-reactive protein, and white blood cell count have been established as independent risk factors for the development of hyperlipidemia in this age group." (PMID 39906294, 2025). "The analysis revealed that BMI, fasting blood glucose, serum uric acid, C-reactive protein, and white blood cell count were significant independent risk factors for hyperlipidemia in the middle-aged and older adult population." (PMID 39906294, 2025). "The levels of creatinine, triglyceride, LDL-C, CRP, and D-dimer were significantly elevated in the PTA_UN patient group compared to healthy individuals, suggesting a high risk for kidney disease, hyperlipidemia, cardiovascular disorder, and thrombosis." (PMID 39534497, 2024). "It is reported that hyperlipidemia is frequently found among patients suffering from RA and significantly linked to the level of C-reactive protein (CRP) and disease activity." (PMID 29558494, 2018). "The positive association persisted when adjusted for traditional cardiovascular risk factors, including hyperlipidemia, anthropometric variables, and CRP." (PMID 23537807, 2013). "The average serum CRP level in a healthy Caucasian is about 0.8 mg/L, but this baseline level can vary widely among individuals due to other factors, including age, gender, blood pressure, hyperlipidemia, and polymorphisms in the CRP gene." (PMID 38156391, 2023). "Hyperlipidemia was associated with 1.49 mg/dL lower CRP, p<0." (PMID 37490455, 2023). "Adding glycosaminoglycan induced inhibition of c-reactive protein activity and caused changes in and sero-biochemical parameters of phospholipids and free fatty acids, which indicated this compound to be potentially treatable for mammalian hyperlipidemia." (PMID 34681728, 2021). "Additionally, serum level of CRP was also profoundly increased in hyperlipidemic model groups, indicating that hyperlipidemia was significantly associated with systemic inflammation." (PMID 24742015, 2014). "Our current study indicates that in rats with hyperlipidemia, metformin and atorvastatin therapy is favorable for NO production and CRP reduction, which might be associated with Rho kinase activity decrease." (PMID 25028180, 2014). "In rats with hyperlipidemia, metformin and atorvastatin therapy is favorable for NO production and CRP reduction, which might be associated with Rho kinase activity decrease." (PMID 25028180, 2014). "Therefore more studies are focusing on novel serum markers, including C-reactive protein and homocysteine, as cardiovascular disease also occurs in many people with normal lipidemia levels and traditional risk factors were unable to predict the occurrence of cardiovascular disease in these patients." (PMID 24751659, 2014). "In summary, our study developed a practical predictive nomogram that identifies seven variables associated with PSS, including CRP, ALB, CK, FBG, hyperlipidemia, sleep disorders, and MMT score, to assess the risk of PSS." (PMID 41432712, 2026). "Regular consumption of an anti-inflammatory diet is associated with beneficial changes in inflammatory markers, including CRP, glycemia, insulinemia, and lipidemia." (PMID 40218947, 2025). "Hyperlipidemia enhance production of proinflammatory markers such as CRP, reactive oxygen species (ROS) and reduce anti‐inflammatory cytokine and adiponectin." (PMID 37970383, 2023). "Deceased patients showed more often hyperlipidemia (p = 0.008), increased CRP values (p = 0.001) and history of device exchange (p = 0.016)." (PMID 37899422, 2023).
hyperlipidemia (continued). "SNPs associated with IL1F10 are associated with serum C‐reactive protein (CRP) concentrations in a genome‐wide association study, and recombinant IL‐38 inhibits CRP and IL‐1β production by PBMC from patients with hyperlipidemia." (PMID 33125159, 2021). "TGA-patients are younger, more often female, have higher prevalence of hyperlipidemia, lower blood glucose levels, lower CRP levels, and lower CHA2DS2-VASc scores compared to AIS-patients." (PMID 34305782, 2021). "PBMC from patients with hyperlipidemia, when treated in vitro with recombinant IL‐38, reduced gene expression and protein secretion of IL‐6, IL‐1β, and CRP." (PMID 33125159, 2021). "Our genetic correlation suggested a consistent direction of CRP with hypercholesterolemia and hyperlipidemia." (PMID 34386016, 2021). "Seven individuals were excluded due to overt diseases: infection with high CRP, extreme hyperlipidemia, hepatitis C antibody positivity." (PMID 33740794, 2021). "In humans, Al-Waili (2004) conducted a series of clinical studies that investigated the effect of honey on a number of metabolic parameters, including cardiovascular risk markers such as C-reactive protein (CRP), homocysteine, and hyperlipidemia." (PMID 32455701, 2020). "Secondary outcomes across statin regimes were compared using serum level of LDL as an indicator for hyperlipidaemia and hs-CRP as the marker for inflammation, three months after PCI." (PMID 32428019, 2020). "In another recently conducted study in Saudi Arabia, the prevalence of hyperlipidemia in patients suffering from RA and its relationship with C-reactive protein level was investigated." (PMID 29558494, 2018). "These recommendations are based on JUPITER trial assessing the benefit of statin treatment in apparently healthy persons with hyperlipidemia (LDL-C < 130 mg/dL) but with elevated high-sensitivity CRP levels (hs-CRP ≥ 2 mg/dL)." (PMID 25807266, 2015). "Results from our current study show that in rats with hyperlipidemia, colchicine therapy is beneficial for reducing CRP level, increasing NO production and decreasing Lp-PLA2 level, which is independent of lipid-lowering." (PMID 24742015, 2014). "Results from our current study indicate that in rats with hyperlipidemia, either metformin or atorvastatin treatment is favorable for reducing CRP level, increasing NO production and decreasing Rho kinase activity." (PMID 25028180, 2014). "The levels of N-acetyl-glycoproteins that serve as inflammatory markers and acute-phase reactant proteins, such as serum amyloid A (apoSAA) and C-reactive protein (CRP), were significantly increased during the early stages of hyperlipidemia (the 4th week)." (PMID 23840531, 2013). "Therefore, investigating the relationship between inflammation and hyperlipidemia using other inflammatory markers, including high-sensitivity CRP, TNF-α, and IL-1β, is necessary." (PMID 40552326, 2025). "Therefore, our interventional clinical study aimed to assess the impact of combined periodontal, endodontic, and dentoalveolar surgical treatments on serum CRP levels and serum lipid components and lipoproteins in patients with hyperlipidemia." (PMID 39797322, 2025). "C-reactive protein, which is measured at lower wavelength, is affected by lipemia." (PMID 38665874, 2024). "Valproate causes hyper homocysteinemia, non-HDLc hyperlipidemia, and high hs-CRP level correlating well with increased risk of atherogenesis." (PMID 37324229, 2023). "Moreover, APTT is influenced by hyperbilirubinemia, hyperlipidemia, anti-phospholipid antibodies, and increased C reactive protein." (PMID 36090551, 2022). "These statins are commonly prescribed as cholesterol-lowering agents in patients with hyperlipidemia and are considered to exert anti-inflammatory activity, as indicated by reduced levels of the inflammatory marker C-reactive protein in patients who are prescribed statins." (PMID 28503146, 2017).
hyperlipidemia (continued). "These investigations may reveal a microcytic anemia, elevated ESR, elevated CRP, and hyperlipidemia." (PMID 23555066, 2013). "In patients with type 1 DM, atherogenic hyperlipidemia was associated with impaired renal function as assessed by decreased GFR, increased microalbuminuria and serum creatinine concentration, and chronic subclinical inflammation (evidenced by the increased ferritin, ESR and CRP)." (PMID 32722394, 2020). "Additionally, serum level of CRP was also profoundly increased in the hyperlipidemia groups." (PMID 25028180, 2014). "Interestingly and importantly, our current study also preliminarily suggested that in the setting of hyperlipidemia, 50 mg/Kg body weight per day of metformin administration was beneficial for NO production increment and CRP level reduction which was consistent to previous studies." (PMID 25028180, 2014). "The results identify CRP, ALB, CK, FBG, hyperlipidemia, sleep disorders, and MMT score as key predictors for PSS." (PMID 41432712, 2026). "This patient had a CK level of 340 U/L, albumin level of 46 g/L, FBG of 6.0 mmol/L, CRP level of 9 mg/L, presence of sleep disorders, a MMT grade of 0–3, and hyperlipidemia." (PMID 41432712, 2026). "Compared with the T2D group, the T2D with hyperlipidemia group had significantly higher levels of TG, TC, LDL-C, ApoB/ ApoA1, FBG, HbA1c, hs-CRP, and PCSK9." (PMID 39951410, 2025). "Our sorbent can be recommended for performingcomplex removal of CRP and atherogenic lipoproteins from the blood plasma inpatients with refractory hyperlipidemia and CVD that are accompanied byelevated levels of CRP." (PMID 35127146, 2021). "This sorbent can be recommended for a complexelimination of CRP and atherogenic lipoproteins from the blood plasma ofpatients with refractory hyperlipidemia and CVD that are accompanied byelevated CRP levels." (PMID 35127146, 2021). "We assessed all risk factors with P values ≤ 0.05 using a univariate logistic regression model (including age, hyperlipidemia, LAA, SUE, NIHSS score, AMCI, hemoglobin, fibrinogen, D-dimer, and CRP)." (PMID 34124248, 2021). "HOMA‐IR and CRP displayed significant correlation with each other, and a gradual increase in the order: control < VFA < lipidemia < glycemia < lipidemia + glycemia." (PMID 32378734, 2020). "IL- 1β inhibition, particularly with canakinumab, has already demonstrated efficacy in reducing cardiovascular events in patients with elevated C-reactive protein, even in the absence of hyperlipidemia." (PMID 40214958, 2025). "We found that lipemia had statistically significant positive interference on C-reactive protein (CRP) in NULM pools, while a negative interference was in IVLE pools." (PMID 38665874, 2024). "Similar to the effect of DD, it is stated in the literature and the kit inserts that there was no interference up to 1000 lipemia index for CRP measurement." (PMID 38665874, 2024). "the female patients had a longer duration of schizophrenia; higher levels of hyperlipidemia, total cholesterol, HDL-C, eGFR, and FABP3, and lower levels of uric acid, creatinine, albumin, hematocrit, hemoglobin, and high-sensitivity CRP, white blood cell count and were older than the male patients." (PMID 37255976, 2023). "Furthermore, in a study conducted on normal individuals and patients with hyperlipidemia, natural honey consumption decreased cholesterol, CRP (C-reactive protein), and homocysteine levels." (PMID 36873120, 2023). "The article by Ridker PM has also received significant attention for demonstrating the potential of statins in reducing the incidence of major cardiovascular events in patients with elevated C-reactive protein but no hyperlipidemia." (PMID 38017531, 2023). "It reduces cerebrovascular events in patients without hyperlipidemia but with raised C-reactive protein (CRP) levels." (PMID 21356305, 2011).
hyperlipidemia (continued). "The Jupiter trial showed that statin therapy in apparently healthy persons without hyperlipidemia but with elevated C-reactive protein levels significantly reduced the incidence of major cardiovascular events." (PMID 20659330, 2010). "The recently published JUPITER study showed that rosuvastatin significantly reduced the incidence of major cardiovascular events in apparently healthy persons without hyperlipidemia but with elevated CRP levels." (PMID 19594891, 2009). "Statins regulate the functions of T and B lymphocytes, dendritic cells, natural killer cells, reduce the production of inflammatory markers (CRP, TNF, IL-1, IL-6) and reduce the incidence of major cardiovascular events in patients with elevated high-sensitivity CRP levels but without hyperlipidemia." (PMID 33479786, 2021). "The absence of interference of lipemia and hemolysis with the CRP measurement was also confirmed in the previous study evaluating the species-specific Gentian Canine CRP Immunoassay, however, the potential interfering effect of bilirubin was not assessed previously." (PMID 28558755, 2017). "Furthermore, in a randomized trial, statin therapy significantly reduced the incidence of major cardiovascular events among people without hyperlipidemia but with elevated CRP level, which further supported the anti-inflammatory effect of statin." (PMID 26644971, 2015). "When categorized by baseline C-reactive protein (CRP; cut point of 2 mg/L), subjects in the lower CRP sub-group benefited more from dietary intervention, including a more increase in cholesterol efflux, a greater reduction in SCD1, and a blunted postprandial lipemia." (PMID 21871057, 2011). "Thus, in this trial on apparently healthy individuals without hyperlipidemia but with elevated high-sensitivity CRP levels, rosuvastatin significantly reduced the incidence of major cardiovascular events." (PMID 21437508, 2011). "JUPITER included nearly 18,000 subjects, which was designed to test the hypothesis that treatment with rosuvastatin for primary prevention would reduce vascular events in relatively healthy people with high-sensitivity C-reactive protein (CRP) but without hyperlipidemia." (PMID 37143855, 2023). "However, considering the association between elevated CRP levels and increased CAD, independent of hyperlipidemia, and the ability of statin therapy to reduce CRP levels regardless of its effect on lipid levels, it is plausible that statins may prevent ACS in individuals with elevated CRP levels." (PMID 37760885, 2023).